RNU6-687P (RNA, U6 small nuclear 687, pseudogene)
Gene: Small nuclear RNA gene on chromosome 10 (54,452,423 to 54,452,511, reverse strand). Ensembl gene ENSG00000252252.
Homologues: Orthologues: chimpanzee U6 (100% identical), macaque U6 (96% identical), dog U6 (69% identical). Paralogues in human: RNU6-59P (79% identical), RNU6-1083P (78% identical), RNU6-945P (78% identical), RNU6-1047P (76% identical), RNU6-1067P (76% identical), RNU6-1131P (76% identical), RNU6-1145P (76% identical), RNU6-1175P (76% identical), RNU6-16P (76% identical), RNU6-242P (76% identical), RNU6-28P (76% identical), RNU6-38P (76% identical), and 1284 more.